RNU4-89P (RNA, U4 small nuclear 89, pseudogene)
Gene: Small nuclear RNA gene on chromosome 3 (196,747,192 to 196,747,324, reverse strand). Ensembl gene ENSG00000272359.
Homologues: Orthologues: chimpanzee U4 (71% identical), rat LOC120099548 (64% identical), dog U4 (57% identical), rat U4 (56% identical). Paralogues in human: U4 (61% identical), RNU4-36P (59% identical), RNU4-53P (59% identical), RNU4-25P (57% identical), RNU4-4P (57% identical), RNU4-91P (57% identical), RNU4-10P (56% identical), RNU4-40P (56% identical), RNU4-59P (56% identical), RNU4-72P (56% identical), RNU4-86P (56% identical), RNU4-49P (55% identical), and 80 more.